EZH2 (enhancer of zeste 2 polycomb repressive complex 2 subunit)
Diseases named in the same sentence as EZH2 in open-access papers (continued):
Sharing a sentence is not in itself a finding about the gene and the disease.
laryngeal squamous cell carcinoma (7 papers, 2020 to 2022). A squamous cell carcinoma that arises from the larynx. "Using tumor xenografts in nude mice, it was shown that the XIST/miR-124/EZH2 axis increased tumor growth in vivo in laryngeal squamous cell carcinoma." (PMID 36362406, 2022). "LncRNA XIST (X-inactive specific transcript) inhibits miR-124 in three types of cancer: bladder cancer, laryngeal squamous cell carcinoma, and tongue squamous cell carcinoma, which activates AR (androgen receptor), EZH2 and JAG1 (jagged 1) proteins." (PMID 36362406, 2022). "A recent study revealed that SOX2-OT interacts with EZH2, recruits EZH2 to DNA to form the polycomb repressive complex 2 (PRC2), induces H3K27me3, and epigenetically inhibits PTEN expression in laryngeal squamous cell carcinoma cells." (PMID 33294436, 2020).
leiomyoma (7 papers, 2018 to 2026). A well-circumscribed benign smooth muscle neoplasm characterized by the presence of spindle cells with cigar-shaped nuclei, interlacing fascicles, and a whorled pattern. "Interestingly, the distal site was associated with increased H3K27Me3 and EZH2 in leiomyoma samples, showing a putative role for EZH2 in the epigenetic regulation of PRICKLE1 in UL." (PMID 39314474, 2024). "Most importantly, the knockdown of EZH2 using siRNA resulted in the restoration of PRICKLE1 in leiomyoma cells." (PMID 39314474, 2024). "Using chromatin immunoprecipitation, we provide evidence for association of EZH2 with the PRICKLE1 promoter and for hypermethylation of H3K27 within the regulatory region of PRICKLE1 in leiomyomas." (PMID 39314474, 2024). "TaqMan qRT-PCR analysis of matched human myometrium and leiomyoma samples confirmed the increased expression of EZH2." (PMID 39314474, 2024). "Analysis of GEO dataset GSE: 13319 showed that EZH2 mRNA levels were significantly increased in leiomyoma samples compared to those in normal myometrium, confirming an inverse correlation with PRICKLE1 expression." (PMID 39314474, 2024). "Further, western blotting analysis of patient samples showed that EZH2 protein expression was higher in leiomyoma samples compared to patient matched normal myometrium with a consistent inverse relation to PRICKLE1 expression." (PMID 39314474, 2024). "Fibroids are characterized by epigenetic gene modifications, and several previous studies have shown overexpression of EZH2, an epigenetic enzyme in fibroids." (PMID 37686244, 2023). "The present study demonstrated the utility of EZH2 immunohistochemistry for differentiating well-differentiated LMS from cellular leiomyoma." (PMID 30120321, 2018). "Additionally, we identify a direct role for the polycomb repressive complex protein EZH2 (enhancer of zeste homolog 2) in the repression of PRICKLE1 in leiomyoma smooth muscle cells." (PMID 39314474, 2024). "In contrast to this hypothesis, our results indicated that EZH2 expression is significantly upregulated in leiomyoma samples both at mRNA and protein levels and this upregulation was inversely correlated with the expression of PRICKLE1 and REST." (PMID 39314474, 2024). "Several studies demonstrated overexpression of EZH2 in leiomyomas." (PMID 36835153, 2023). "The transcriptional level analysis showed that the expression of EZH2 mRNA in LMS is higher than that in leiomyoma and myometrium, which suggested that the upregulation of EZH2 expression in LMS may occur at the transcriptional level." (PMID 30120321, 2018). "Our results support a novel ERα/ EZH2 – PRICKLE1 mediated, REST- target-specific gene derepression model in the pathogenesis of leiomyomas." (PMID 39314474, 2024). "Totally, EZH2 protein was found to have a sensitivity of 81.25% and specificity of 100% in distinguishing LMS from leiomyoma." (PMID 30120321, 2018). "EZH2 protein was found to have a sensitivity of 81.25% and specificity of 100% in distinguishing LMS from leiomyoma." (PMID 30120321, 2018). "The involvement of many proteins such as FN1, COL1A1, BMP7, CCND1, EZH2, HMGA2, AhR, and E2F1 shown in the protein–protein interaction networks are well known in leiomyoma pathogenesis; others, such as SOX2, REN, PPARG, ABCB1, and NR3C1 are novel and require further investigation." (PMID 36835153, 2023). "Fib-EXO increased the expression of vimentin, EZH2, DNMT1, TGF-β3, and c-MYC, and phosphorylated p65 protein, reduced COL1A1 and COL3A1 expression, and decreased miR-133a, miR-29, and miR-200c while increasing miR-21 in cultured myometrial smooth muscle cells, mirroring changes observed in fibroids." (PMID 42008339, 2026). "Furthermore, siRNA knockdown of EZH2 in cultured primary LSMCs resulted in the increase of PRICKLE1 expression, showing that EZH2 is overexpressed in leiomyomas, and may play a role in the repression of PRICKLE1." (PMID 39314474, 2024).
leiomyoma (continued). "Thus, LINC00337 may be involved in the stimulation of cell proliferation in leiomyomas, since leiomyomas express higher levels of E2F1, EZH2, and DNMT1." (PMID 38279317, 2024). "Conclusively, the high expression of EZH2 is a promising marker in distinguishing well–differentiated LMS from cellular leiomyoma, or well–differentiated ERMS from fetal rhabdomyoma, and the upregulation of EZH2 protein expression may occur at transcriptional level." (PMID 30120321, 2018). "The results demonstrated that EZH2 protein was detected in 81.25% (26/32) of LMS and 70.58% (36/51) of RMS, whereas none of leiomyoma (n = 16), rhabdomyoma (n = 15) and normal tissues (n = 31) showed positive immunostaining (p < 0.05)." (PMID 30120321, 2018).
lymphoid neoplasm (7 papers, 2009 to 2025). A neoplasm composed of a lymphocytic cell population which is usually malignant (clonal) by molecular genetic and/or immunophenotypic analysis. "However, large-scale cancer genome sequencing identified coding mutations within EZH2 gene in various myeloid and lymphoid neoplasms, suggesting a tumor-suppressive role for EZH2." (PMID 25542019, 2014). "Thus, it looks reasonable to prioritize the discovery of new drug combination associating EZH2 inhibitors with other compounds targeting key signaling pathways in order to prevent and/or overcome the occurrence of EZH2i resistance in lymphoid neoplasm with mutated EZH2." (PMID 31681423, 2019). "The histone lysine methyltransferase EZH2 is frequently altered in lymphoid tumors." (PMID 37297005, 2023). "Thus, eventual recruitment of DNMTs by EZH2 can then lead to a high level of aberrant DNA methylation in precursor and germinal center lymphoid neoplasms." (PMID 19750229, 2009). "We postulate that germinal center lymphomas like DLBCL, INT, mBL and FL and precursor lymphoid neoplasms like pre B-ALL and T-ALL are initiated or frozen in developmental stages with proliferating cells and high EZH2 expression." (PMID 19750229, 2009).
malignant mesothelioma (7 papers, 2018 to 2024). A malignant neoplasm of the pleura or peritoneum, arising from mesothelial cells. "Given these encouraging preclinical results, it will be important to clinically explore dual EZH2/FGFR inhibition in patients with BAP1-deficient malignant mesothelioma and justify further exploration in other BAP1 loss–associated tumors." (PMID 38054839, 2024). "Taken together, our in vitro results show a high synergistic potential for combining FGFR and EZH2 inhibition against BAP1-deficient malignant mesothelioma." (PMID 38054839, 2024). "In malignant mesothelioma, it was demonstrated that EZH2 mRNA expression was elevated, yet EZH2 IHC expression and its association with BAP1 in malignant mesothelioma have not been fully understood." (PMID 34257556, 2021). "There was a statistically significant association between BAP1 and EZH2 expression (p = 0.008), where 67.3% of cases of BAP1 loss showed low EZH2 and 62.5% of malignant mesothelioma cases with retained BAP1 showed high EZH2 expression." (PMID 34257556, 2021). "Immunohistochemical detection of BAP1 and EZH2 is a reliable marker for differentiating benign mesothelial proliferation from malignant mesothelioma." (PMID 37461124, 2023). "The deletion of BAP1 and high expression of EZH2 were both observed in malignant mesothelioma, which were merely observed in benign lesions." (PMID 36195655, 2022). "High EZH2 expression has been described in various cancer types, but only a few studies have investigated EZH2 expression in malignant mesothelioma." (PMID 34257556, 2021). "Suppression of EZH2 using RNA interference was found to decrease the cancerogeneity of malignant mesothelioma cells." (PMID 33849532, 2021). "In addition, recent literature suggests a critical role of many epigenetic modulators such as KDM6A, SETD2, SETDB6, and EZH2 in malignant mesothelioma development." (PMID 38054839, 2024). "5-hmC loss and increased EZH2 expression are novel markers for the diagnosis of malignant mesothelioma but are not widely used yet." (PMID 35205689, 2022). "EZH2 overexpression is reported in different cancers, but its relation to BAP1 in malignant mesothelioma has not been fully understood." (PMID 34257556, 2021).
malignant peripheral nerve sheath tumor (7 papers, 2015 to 2022). Malignant peripheral nerve sheath tumor (MPNST) is a rare and often aggressive soft tissue sarcoma occurring in a wide range of anatomical sites. "In conjunction with additional tumor suppressors, the PRC2 subunits EED and SUZ12 (but not EZH2) are mutated in 85% of malignant peripheral nerve sheath tumors (MPNST) that develop in patients with NF1 mutations." (PMID 34617019, 2021). "Previously, we demonstrated that the EZH2/miR-30d/karyopherin (importin) beta 1 (KPNB1) signaling pathway is critical for malignant peripheral nerve sheath tumor (MPNST) cell survival in vitro and for tumorigenesis in vivo." (PMID 25890085, 2015). "For example, in malignant peripheral nerve sheath tumor, PRC2 is recurrently inactivated through component EED or SUZ12 but not EZH2, despite a complete loss of H3K27me3." (PMID 36612203, 2022).
metastatic carcinoma (7 papers, 2012 to 2024). A carcinoma which has spread from the original site of growth to another anatomic site. "Our results in this study are in favor of a strong inverse correlation between Snail/Slug and miR-101, and the loss of miR-101 and concomitant elevation of EZH2 is most pronounced in metastatic cancer." (PMID 25762643, 2015). "In matched primary and metastatic cancers, both HOTAIR and EZH2 had increased expression in the metastatic carcinomas." (PMID 23133536, 2012). "Though both HOTAIR lncRNA and EZH2 protein have been found to be overexpressed in both primary and metastatic breast carcinomas, their expression in matched primary and metastatic cancers has yet to be explored." (PMID 23133536, 2012). "EZH2 positivity in UCS was previously reported in a single effusion cytology specimen in one study, which investigated the utility of EZH2 as a single immunomarker in the diagnosis of metastatic carcinoma in effusion samples." (PMID 38146588, 2023). "Thus, the data support increased expression of both EZH2 and HOTAIR in the metastatic cancers, compared to primary carcinoma." (PMID 23133536, 2012). "Overall, TGFB1-mediated, EZH2-catalyzed SMAD3 K53/K333 methylation could function as a predictive marker of survival for patients with cancer and potentially serve as a therapeutic target for patients with metastatic cancer." (PMID 35085106, 2022). "However, upon comparing pairs of primary versus metastatic carcinoma, both HOTAIR and EZH2 expressions more often had equivalent (31% and 52%, respectively) or increased expression (52% and 40%, respectively) in the metastasis compared to the primary carcinoma." (PMID 23133536, 2012).
Oral leukoplakia (7 papers, 2013 to 2025). A thickened white patch on the oral mucosa that cannot be rubbed off. "Although such association has not been described in OSCC, mostly hypermethylated according to our results, EZH2 higher expression was shown to be an independent factor for OSCC development within oral leukoplakia patients and associated with radioresistance." (PMID 34208581, 2021). "Furthermore, EZH2 can induce malignant transformation of oral leukoplakia and epithelial–mesenchymal transition in HNSCC." (PMID 38600608, 2024). "Additionally, EZH2 has been found to initiate oral leukoplakia malignant transformation and epithelial-mesenchymal transition in HNSCC." (PMID 26378043, 2015). "Secondly, the unique specificity of EZH2 in HNSCC tissues, which can induce malignant transformation of oral leukoplakia and EMT processes, holds paramount importance in comprehending the initiation and progression of HNSCC." (PMID 38600608, 2024).
papillary thyroid carcinoma (7 papers, 2019 to 2026). "In the context of EZH2‐mediated dedifferentiation, EZH2 represses PAX8 gene expression by targeting its promoter in ATC, and in papillary thyroid carcinoma (PTC) cells, a variant of WDTC, Tazemetostat treatment enhances TDGs expression and iodide uptake." (PMID 41147659, 2026). "lncRNA MIAT can reportedly suppress EZH2 expression and promote papillary thyroid carcinoma cell invasion via miR-15033." (PMID 38383737, 2024).
stomach cancer (7 papers, 2016 to 2024). "EZH2 protein level of gastric tumor tissue was reduced more than 50% by H2 exposure, which was enhanced by miR-124-3p and suppressed by lncRNA MALAT1." (PMID 33482814, 2021). "A previous study revealed that EZH2 is the target of miR-124 in gastric tumor cells." (PMID 33040049, 2020). "Interestingly, EZH2 has been considered as a target of miR-124 in gastric tumors." (PMID 33040049, 2020).
urothelial carcinoma (7 papers, 2017 to 2025). A malignant neoplasm derived from the transitional epithelium of the urinary tract (urinary bladder, ureter, urethra, or renal pelvis). "A recent basic study showed novel histone methyltransferase EZH2 inhibitor can further reduce progression of urothelial carcinoma." (PMID 36368976, 2022). "In a clinical trial in patients with urothelial carcinoma, the synergistic effect of EZH2 inhibition and anti-PD1 treatment is currently investigated (NCT03854474)." (PMID 32041674, 2020). "Here, we attempt to better define the long-term outcomes of radical cystectomy (RC) for urothelial carcinoma (UC) in a Chinese population and to investigate the relationship between EZH2 protein expression levels and the clinicopathological parameters and outcomes in patients with UC." (PMID 30542123, 2018).
acute liver failure (6 papers, 2021 to 2025). Rapid deterioration of liver function causing encephalopathy and coagulopathy. "HBV X protein (HBx) facilitates ferroptosis in acute liver failure by EZH2-mediated SLC7A11 suppression." (PMID 39518098, 2024). "Similar to the results of our experiments, EZH2 was reported to promote ferroptosis by suppressing SLC7A11 expression in a D-galactosamine-induced acute liver failure model." (PMID 38169402, 2024). "For instance, EZH2-mediated SLC7A11 modulated ferroptosis in acute liver failure." (PMID 35997855, 2023).
anemia (6 papers, 2021 to 2025). A reduction in the number of red blood cells, the amount of hemoglobin, and/or the volume of packed red blood cells. "The RUNX1 mutation was associated with worse OS and a higher AML transformation rate, while the co‐occurrence of SF3B1 with EZH2 may be associated with more severe anemia and transfusion dependency." (PMID 40342275, 2025). "Leukemic transformation occurredin two patients (family 1:proband 1; duration:12 years; Family 1; proband’s young sister; duration 12 years), proband 1 harbouring EZH2 (c.707delC (p.Thr236fs mutation experienced erythropoietic failure (normoblasts:2%) with severe anemia." (PMID 35798703, 2022). "Some EZH2 inhibitors similar to SHR2554, such as tazemetostat, also had similar adverse effects such as thrombocytopenia, neutropenia, and anemia." (PMID 35841331, 2023).
asthma (6 papers, 2018 to 2024). "Furthermore, Ezh2 deficiency in vivo was found to worsen mouse asthma allergy and associated with accumulation of Th2 cytokine-producing cells." (PMID 30452487, 2018). "The enrichment results of KEGG revealed that EZH2 expression was closely related to homologous recombination, cell cycle, nucleotide excision repair, asthma, complement and coagulation cascades, primary bile acid biosynthesis, and arachidonic acid metabolism." (PMID 36545914, 2023). "In a mouse model of asthma, EZH2 promoted asthma development through the FOXO3-miR-34b-BTG2 axis." (PMID 39108751, 2024). "Among the eight TFs, EZH2 and POLR2A have been associated with the pathogenesis of asthma." (PMID 37569643, 2023).
colon adenocarcinoma (6 papers, 2017 to 2025). "Our analysis using the TCGA database revealed that EZH2 and MYC were upregulated across multiple human tumors, including stomach adenocarcinoma (STAD), colon adenocarcinoma (COAD), and rectum adenocarcinoma (READ)." (PMID 39823459, 2025).
experimental autoimmune encephalomyelitis (6 papers, 2016 to 2023). An autoimmune demyelinating disease of the central nervous system that is produced experimentally in animals by the injection of homogenized brain or spinal cord in Freund's adjuvant. "Furthermore, Ezh2 deficiency in microglia in vivo, achieved by crossing Ezh2 floxed mice with Cx3cr1-CreER mice, confirmed in an animal model of experimental autoimmune encephalomyelitis, that EZH2 facilitates activation of microglia toward a pro-inflammatory M1 phenotype." (PMID 30123114, 2018). "Ezh2-deficient T effector cells neither provided a protective response to T. gondii infection nor mediated autoimmune colitis, and Ezh2-ablation in Treg failed to constrain autoimmune colitis or experimental autoimmune encephalomyelitis." (PMID 27784285, 2016). "Interestingly, mice lacking the EZH2 gene exhibited attenuated experimental autoimmune encephalomyelitis (EAE) disease progression due to the inability of EZH2-deficient cells, particularly neutrophils and dendritic cells, to reach the site of inflammation." (PMID 30367633, 2018).
gestational diabetes (6 papers, 2020 to 2025). Carbohydrate intolerance first diagnosed during pregnancy. "By contrast, an earlier study showed that EZH2 is downregulated in HUVECs from patients with gestational diabetes." (PMID 38580969, 2024). "miR-195-5p targets EZH2 to inhibit gestational diabetes mellitus-induced human umbilical vein endothelial cells’ proliferation and promote their apoptosis." (PMID 34790697, 2021). "In human fetal endothelial cells (ECs) of the umbilical cord vein (HUVECs) in gestational diabetes mellitus patients, miR-101 was upregulated, leading to H3K27me3 downregulation by targeting EZH2." (PMID 32070413, 2020). "Findings have shown that EZH2 expression is down‐regulated in gestational diabetes mellitus (GDM), and overexpression of EZH2 promotes the proliferation and hinders the apoptosis of human umbilical vein endothelial cells." (PMID 37985432, 2024). "In a recent study, human umbilical vein EC isolated from gestational diabetes mellitus-affected individuals (also referred as GDM-HUVECs) displayed impaired endothelial function via miR-101 upregulation and a concurrent reduction in EZH2 and H3K27me3 levels." (PMID 34685528, 2021).